IFNG (interferon gamma)
Diseases named in the same sentence as IFNG in open-access papers (continued):
Sharing a sentence is not in itself a finding about the gene and the disease.
HIV-1 infection (continued). "In long-term HIV-1 infection, ADCC activities mediated by DN CD56+ T subset were significantly declined (CD107a: P = 0.018; IFNγ: P = 0.010), indicating a functional impairment of the subset." (PMID 27814766, 2016). "The elevation of multifunctional cytokines such as IFNγ and TNFα, can either enhance or control HIV-1 infection depending on the clinical stage of HIV-1 infection." (PMID 24454311, 2014). "In samples drawn before HIV-1 infection, MAIT cell responses to the cytokine stimulus recapitulated the pattern previously reported for healthy donors, with higher IFNγ expression in the CD56+ MAIT cells compared to their CD56− counterparts (p < 0.01; Wilcoxon Signed Rank test)." (PMID 31937782, 2020). "Subsequent, in vitro studies demonstrated that IFNγ treatment can enhance HIV-1 infection in both primary macrophages and CD4+ T cells, suggesting that these immune cell subsets were responsible for the original observation of HIV-1 infection of PBMC." (PMID 24454311, 2014). "Moreover, HIV-1 neutralizing antibodies, T cell responses, and specifically T cell produced IFNγ responses that were detected in the vaccinees did not significantly affect the HIV-1 infection rate." (PMID 24454311, 2014). "In response to opsonised IE, HIV-1 infection significantly reduced IL-6 release (1,116 pg/mL (IQR: 352–3,387) compared to 1,552 pg/mL (IQR: 889–6,331); p = 0.0078) and IL-1β release (16 pg/mL (IQR: 7–21) compared to 33 pg/mL (IQR: 27–65); p = 0.0078) from mock-infected IFNγ primed MDM." (PMID 22363802, 2012). "Interestingly, Alprazolam can also activate STAT5 in non-HIV-1 infected cells, therefore, despite CD8+ T cells being a non-target to HIV-1 infection, the activation of STAT5 in CD8 cells may have allowed increased biding of STAT5 on the IFNγ promoter and jump-start cytokine production." (PMID 34367046, 2021).
leprosy (107 papers, 2007 to 2025). Leprosy is a chronic infectious disease affecting primarily the skin and peripheral nervous system. "PB leprosy is associated with a robust Th1 response, marked by high levels of pro-inflammatory cytokines such as interferon-gamma (IFN-γ), facilitating effective cell-mediated immunity." (PMID 39498129, 2024). "We validated NOD2 and IFNG associations with resistance and risk of leprosy, respectively, in the Amazon ethnic admixed population." (PMID 32433683, 2020). "On the contrary, in the reaction-free leprosy group, interferon-gamma (IFN-γ) levels were dependent on the association between TLR2 and TLR1 (0.8735)." (PMID 31781675, 2019). "Although the results have not been confirmed, the rs692527 and rs34856358 variants of the MRC1 gene were found to be associated with PB leprosy, and the rs3138557 variant of the IFNG gene was associated with MB leprosy." (PMID 26793196, 2015). "In case-control studies, SNPs in the IL10 gene (−819 C>T) and IFNG gene (+874 T>A) were reported to be associated with susceptibility and protection in leprosy, respectively." (PMID 23798993, 2013). "These two cytokines and IFNG are associated with leprosy granuloma formation." (PMID 38440733, 2024). "Similarly, leprosy reversal reactions, characterised by painful inflammation of leprosy lesions, are associated with infiltration of IFNγ producing CD4+ T cells." (PMID 36121873, 2022). "Studies involving the injection of recombinant IFNγ into dermal lesions have shown faster clearance of bacilli compared to a control group that received only MDT, further supporting the role of IFNγ in eliminating leprosy bacilli." (PMID 38818380, 2024). "A meta-analysis using data from different populations also found that IFNG +874 A/T showed a protective effect for leprosy." (PMID 32373110, 2020). "In one of these cases, a man with lepromatous leprosy and mucosal leishmaniasis, skin reaction and IFNγ production against Leishmania antigens were strong, whereas the responses against M. leprae antigens were almost absent." (PMID 29494584, 2018). "Summary of associations between genes of innate immune response MICA, MICB, KIR, TNF, LTA, BAT1, IFNG, and leprosy." (PMID 26793196, 2015). "It shows strong T-cell response in leprosy patients, elicits specific delayed type hypersensitivity, and stimulates IFNγ production also." (PMID 25101267, 2014). "Early studies of leprosy intradermal cytokine expression determined that leprosy polarity is associated with TH2 cytokines IL4, IL5, IL10 in lepromatous lesions, and TH1 polar cytokines, IFNG, IL2, in tuberculoid lesions." (PMID 25412496, 2014). "In agreement with our previous findings, antigens ML0840 and ML2044 induced significantly greater IFNγ secretion in WBA using blood from TT/BT leprosy patients than WBA using EC blood." (PMID 21269435, 2011). "The ML0405 and ML2055 antigens each induced secretion of IFNγ greater than 50 pg/ml in 95% (19 of 20) of TT/BT leprosy patients examined." (PMID 21269435, 2011). "Clofazimine induces IFNγ production and downregulates suppressor T-cells in M. leprae-infected cells suggesting the effectiveness of clofazimine against leprosy is through modulation of lipid metabolism and activation of effector immune repose in M. leprae -infected host cells." (PMID 35867720, 2022). "Here, we investigated whether SNPs located in eleven genes: CCDC122/LACC1, IFNG, IL6, IL10, IL23R, LRRK2, NOD2, PACRG/PRKN, TLR1, TNF and TYK2 are associated to leprosy susceptibility in a population in the North of Brazil." (PMID 32433683, 2020). "In Mycobacterium leprae infection, patients with lepromatous type, a progressive form of leprosy, possess an IFNβ signature in their skin lesions, while patients with the self-limiting tuberculoid form of leprosy have an IFNγ signature at the site of infection." (PMID 30918279, 2019).
leprosy (continued). "The markers included 11 SNPs selected to replicate the previously reported associations of the TLR1, NOD2, and IL6 genes and the remaining SNPs in 4 candidate genes TNF, LTA, IFNG, and IL10, in reference to markers previously associated with leprosy per se as an outcome." (PMID 28715406, 2017). "In contrast with the leprosy-specific cellular responses of the proteins categorized above, several of the recombinant proteins tested, in addition to the TT/BT leprosy group, stimulated IFNγ release in the TB or EC groups (ML0022, ML2358, ML2346, ML2380, ML2541, ML2603 and ML2203)." (PMID 21269435, 2011). "The identification of Th17 cells as major inducers of antimicrobial genes in RR lesions through the expression of TNF, IFNG, and IL17A provides important new insights into the role of this T cell subset in leprosy immunopathogenesis." (PMID 40569678, 2025). "The spectrum of leprosy disease is defined by host T cell responses, with tuberculoid disease being characterised by robust CD4+ T cell IFNγ responses and patients with lepromatous disease failing to mount anti-M. leprae cell-mediated responses." (PMID 36121873, 2022). "Consistent with this prediction, the ML0405 protein was recognized by IFNγ release in WBA using TT/BT leprosy patient blood and by serum IgG from LL/BL leprosy patients." (PMID 21269435, 2011). "A qPCR performed to evaluate pro- and anti-inflammatory related gene expression in skin lesions of leprosy patients revealed that pro-inflammatory genes STAT1, TNF, IFNG, IL15 and CSF2 are increased in PB cells, whereas anti-inflammatory MSR1 and PPARG genes are increased in MB cells." (PMID 34354699, 2021). "In the TT form of leprosy, activation of the classical pathway by M1 macrophages induces the production of tumor necrosis factor-alpha (TNF-α), interferon-gamma (IFN-γ), and induced nitric oxide synthase (iNOS), which induce the generation of free radicals that destroy the bacillus." (PMID 30442123, 2018). "Since macrophages are the main cells that exert microbicidal activity in leprosy, many studies have already described the role of these cells in the response to cytokines, including tumor necrosis factor-alpha (TNF-α) and interferon-gamma (IFN-γ)." (PMID 29234318, 2017). "Interestingly, our study demonstrated that CCL17 and CCL18 distinguished leprosy polarity with greater accuracy than the traditional TH1 and TH2 cytokines (IL10, IFNG)." (PMID 25412496, 2014). "We previously demonstrated that the ML0276 protein induces IFNγ secretion from TT/BT leprosy patient and HHC blood but not from controls." (PMID 21269435, 2011). "We have additionally investigated the classic candidate genes TNF/LTA, IFNG, and IL10, which were consistently associated with leprosy per se but, despite the central roles of these cytokines in leprosy reactions, were not genetically associated with reaction outcomes in our study." (PMID 28715406, 2017). "Although not recognized in terms of IFNγ production within WBA with LL/BL blood, as we previously reported, the ML0405 and ML2331 proteins were well recognized by serum IgG from LL/BL leprosy group." (PMID 21269435, 2011). "Thus, our data identifies five M. leprae proteins (ML0840, ML2044, ML1632, ML1685 and ML1556) that, despite stimulating IFNγ production in WBA using blood from the TT/BT and HHC groups, are not detected by serum IgG responses of leprosy patients." (PMID 21269435, 2011).
myocarditis (105 papers, 2009 to 2026). Myocarditis is a condition that is characterized by inflammation of the heart muscle (myocardium). "The predominant activity of type 1 T helper (Th) cells and their associated cytokines including interferon γ (IFNγ) was attributed to the observed myocarditis in MRL-Pdcd1−/− mice." (PMID 39039301, 2025). "Together, evidence suggests that myocarditis and IFNγ signaling plays a major pathogenic role in CCC development and severity, although downstream events leading to the heart disease phenotype are still obscure." (PMID 33351798, 2020). "Conversely, IFNγ transgenic mice develop chronic myocarditis leading to severe cardiomyopathy, and IFNγ plays a critical role in doxorubicin-induced cardiomyopathy." (PMID 39285385, 2024). "Considering IFNγ signaling-recipient cells, decreased motif activity in STAT1 across multiple cell types in myocarditis suggests that the response to IFNγ secreted from cytotoxic NK and CD8 effector cells was downregulated." (PMID 37264110, 2023). "IL18 is expressed in myocardium early in the course of experimental myocarditis induced by T. cruzi, leading to production of IFNγ." (PMID 33193300, 2020). "More importantly, our findings place CCL3 as a key chemokine in chronic T. cruzi infection, as a putative sponsor for the CD8+ T-cells and macrophage-enriched myocarditis, in a scenario with abundant IFNγ, TNF and CCL3." (PMID 32194558, 2020). "Compared to saline-injected mice, anti-TNF-treated mice showed reduced number of Pfn+ cells but similar number of IFNγ+ cells infiltrating the cardiac tissue, supporting that Infliximab remolded chronic T. cruzi-induced myocarditis." (PMID 25140115, 2014). "The inflammatory response to myocarditis is characterized by a Th1-type immune response, therefore it is possible that the upregulation of IFNγ after MSC-injection was important for the activation of naïve and Tr1 regulatory T cells." (PMID 22815907, 2012). "Distinct from other cardiomyopathies, CCC displays a helper T-cell type 1 (Th1-T) cell–rich myocarditis with abundant interferon-gamma (IFN-γ) and tumor necrosis factor-alpha (TNF-α) and selectively lower levels of mitochondrial energy metabolism enzymes and high-energy phosphates in the heart." (PMID 40297326, 2025). "IRF1, a target gene of the IFNγ signaling pathway, was also downregulated at the myocarditis state." (PMID 37264110, 2023). "However, it was shown in the framework of the study already mentioned that blockade of key effector cytokine Th1 cells—IFNγ—due to knock-out or monoclonal antibodies in vivo contributed to the progression of myocarditis in mice." (PMID 36674665, 2023). "So far, a direct pathogenic role has been described for both activated Th17 and Th1 effector CD4+ T cell subsets, though Th1 effector T cell-derived interferon-gamma was shown to limit myocarditis severity and prevent transition to inflammatory dilated cardiomyopathy." (PMID 30035131, 2018). "Our data suggest that a few microRNAs may potentially regulate multiple key pathogenetically relevant pathways and processes, including fibrosis, hypertrophy, myocarditis and arrhythmia, IFNγ- and Nrf2-modulated and mitochondrial genes." (PMID 29269773, 2017). "We, then, examined whether anti-TNF therapy influenced the balance of cytotoxic (Pfn+) and inflammatory (IFNγ+) cells composing the chronic T. cruzi-induced myocarditis." (PMID 25140115, 2014). "A recent study supports that at 30 dpi a proportion of infiltrating cardiac cells coexpress IL-10 and IFNγ and may play a beneficial role in T. cruzi-elicited myocarditis." (PMID 22532799, 2012). "It has also been reported that IFNγ acts as a positive regulator of CD25 expression on CD4+ T cells in a mouse model of myocarditis, though it is unclear whether IFNγ directly or indirectly controls CD25 expression in CD4+ T cells." (PMID 21731484, 2011).
myocarditis (continued). "Although IFNγ is increased in our model of CVB3 myocarditis in males, we showed that elevated IFN levels in male BALB/c mice with myocarditis are mediated by IL-18, which is downstream from TLR4, rather than traditional STAT4/IL-12 transcriptional activity." (PMID 39696682, 2024). "Because CD4+ T cells were increased by BPA exposure in drinking water, we examined whether IFNγ, IL-4, and/or IL-17A cytokine levels were altered in the heart during acute CVB3 myocarditis following BPA exposure." (PMID 31551929, 2019). "In this study we found that exposure to BPA in drinking water elevated proinflammatory cytokines/ receptors in the heart of female mice during CVB3 myocarditis that would typically be elevated in male mice or men with mycarditis such as TLR4, caspase-1, IL-1β, IL-17A, and IFNγ." (PMID 31551929, 2019). "Therefore, adopting a murine model of chronic T. cruzi-elicited CD8-enriched myocarditis, we analyzed CD8+ T-cells to clarify whether they are multifunctional (IFNγ+Pfn+) or segregated into inflammatory (IFNγ+) and cytotoxic (Pfn+) cells." (PMID 22532799, 2012). "In the case of experimental animals, which had no responses, Th1 mediated and Th17 (IL17A−/− IFNγ−/−), virus-initiated development of myocarditis was accompanied by activation of Th2 cells and the development of eosinophilic myocarditis, clinically similar to human myocarditis." (PMID 36674665, 2023). "We do not observe a sex difference in viral levels in the heart during myocarditis in our CVB3 mouse model and sex differences in IFNγ are not mediated by classic IFN signaling." (PMID 39696682, 2024). "The intensity of acute and chronic T. cruzi-elicited myocarditis is related to the concentrations of the CC-chemokines CCL3/MIP-1α and CCL5/RANTES, but not to the concentrations of IFNγ and TNF in the cardiac tissue." (PMID 22532799, 2012). "IL-17A, but not IFNγ, has been shown to promote remodeling and fibrosis and progression from acute myocarditis to chronic myocarditis and DCM in the CVB3 and experimental autoimmune models of myocarditis in male mice and in male patients with myocarditis." (PMID 31551929, 2019). "Considering the recent finding showing a role for interleukin (IL)-10 in T. cruzi-triggered myocarditis, we studied whether or not CD8+IFNγ+ cells coexpress IL-10 during T. cruzi infection." (PMID 22532799, 2012).
uveitis (99 papers, 2008 to 2026). An inflammatory process affecting a part of or the entire uvea. "Research work indicates that uveitis is strongly associated with inflammatory and immune cytokines, including tumor necrosis factor, interleukin 1 (IL-1), IL-2, IL-6, IL-8, and interferon gamma (IFN-γ)." (PMID 40687721, 2025). "JAK inhibitors block multiple pro-inflammatory cytokines implicated in human uveitis such as IL-6 and IFNγ, resulting in disruption of Th1 differentiation." (PMID 35998207, 2022). "In contrast to the joint and spine, wherein interferon-gamma (IFNγ) deficiency reduced disease, IFNγ deficiency worsened uveitis." (PMID 22269151, 2012). "The present study demonstrates an important regulatory role for IFNγ in uveitis associated with a murine model of spondyloarthropathy." (PMID 22269151, 2012). "Mice deficient in IFNγ develop exacerbated uveitis that is characterized by infiltrating granulocytes, whereas the joint and axial disease are ameliorated by IFNγ deficiency." (PMID 22269151, 2012). "We conclude that IFNγ exerts a critical regulatory role in suppression of IL-17, which is pathogenic in uveitis." (PMID 22269151, 2012). "Interestingly, among patients with uveitis of undetermined cause, some exhibited TB immunoreactivity as detectable through interferon-gamma release assays (IGRA) or tuberculin skin tests (TST)." (PMID 41018498, 2025). "Previous reports addressing the pathogenesis of uveitis have implicated T-helper type 1 (Th1) and Th17 lymphocytes and their predominantly produced cytokines, interferon-gamma (IFN-γ) and interleukin (IL)-17, respectively, as the cause of exacerbated inflammation associated with uveitis." (PMID 40270958, 2025). "Interferon-gamma has been shown to be associated with tuberculous-initiated uveitis." (PMID 36157069, 2022). "Likewise, IL-17 blockade abolished the retinal vasculitis and retinal folding found in several IFNγ-deficient mice with PG-induced uveitis." (PMID 22269151, 2012). "Comparison of patients with uveitis only revealed comparable results with significantly (p < 0.001) higher serum anti-IFNα2 and anti-IFNγ antibody levels in TBU compared to those in SU; these concentrations were again comparable to Indonesian HCs." (PMID 39309852, 2024). "Focusing on patients with uveitis, SU showed increased IFNα2 (p = 0.004) and IFNγ (p < 0.002) serum concentrations compared to that in TBU." (PMID 39309852, 2024). "Key cytokines associated in uveitis include interleukins (IL), specifically IL-6 and IL-17, tumor necrosis factor alpha (TNF-α), and interferon gamma (IFN-γ), each exhibiting distinct effects on the pathogenesis of uveitis." (PMID 39075390, 2024). "In uveitis cases only, IFNγ positivity was observed more frequently in SU (9/13:69 %) compared to TBU (2/12:17 %; p = 0.015; Fisher's exact test)." (PMID 39309852, 2024). "Uveitis in VKHD patients showed the dominant role of clonally expanded Th1‐like effector CD4+ T cells expressing IFNG and TNF." (PMID 37720629, 2023). "The presence of cytokines (interferon gamma, IL-2) in ocular tissue obtained from patients with intraocular inflammation (uveitis) has been confirmed." (PMID 35160111, 2022). "Cytokines were clustered in two major groups: the first one included cytokines with the highest fold difference in concentrations between patients with uveitis and controls: IL-6, IL-8, IFNγ, TNFα, IP-10, G-CSF, IL-1ra." (PMID 32210963, 2020). "The specific presence of IFNγ and TNFα in AH samples only from patients with uveitis renders these cytokines promising targets in a therapeutic perspective." (PMID 32210963, 2020). "Increased intracellular IL-10 and IL-17A and decreased intracellular IFNγ levels were found in CD4+ T-cells from active uveitis, 6 months after starting treatment, when the disease had clinically resolved." (PMID 29774027, 2018).